HABP2 (hyaluronan binding protein 2)
Diseases named in the same sentence as HABP2 in open-access papers (continued):
Sharing a sentence is not in itself a finding about the gene and the disease.
lung carcinoma (2 papers, 2015 to 2019). "Our data that HABP2 promote uPA activation provides important mechanistic insights into HABP2 involvement in diseases associated with vascular dysfunction including lung cancer." (PMID 26258071, 2015). "In lung cancer, the up-regulation of hyaluronan in the extracellular matrix regulate the activity of HABP2 and its regulation of cancer progression has been shown in LUAD, in agreement with our results." (PMID 31429720, 2019). "The hyaluronan binding protein 2 (HABP2) is an extracellular serine protease, which is up-regulated in LUAD and down-regulated in LUSC has been associated with lung cancer." (PMID 31429720, 2019). "Taken together, our data suggest a possible direct effect of HABP2 overexpression on lung cancer progression, and provide a potential functional explanation for the increased HABP2 expression observed in lung cancer." (PMID 26258071, 2015). "Based on the recent published data indicating HABP2 are increased in lung cancer, this study investigated the functional effects of HABP2 in human NSCLC cells both in vitro and in vivo." (PMID 26258071, 2015). "Immunohistochemical analysis was performed on lung cancer patient samples using anti-HABP2 antibody." (PMID 26258071, 2015). "We have also discovered a differential effect of HA on HABP2 and uPA-regulated lung cancer progression based on its molecular weight." (PMID 26258071, 2015). "Here, we present evidence of a role for HABP2 in the regulation of urokinase plasminogen activator (uPA) activation during lung cancer progression." (PMID 26258071, 2015). "Quantitation of nestin immunoreactivity revealed ~10-fold increase in lung metastasis from HABP2 overexpressing primary tumors indicating the importance of this molecule in lung cancer progression." (PMID 26258071, 2015). "Given previous published data indicating HABP2 is increased in lung cancer, we undertook a series of in vitro and in vivo experiments to examine the direct effects of HABP2 in lung cancer progression using human NSCLC cells." (PMID 26258071, 2015). "Since there is an intimate relationship between HABP2 and uPA often leading to reciprocal protease activation, we next focused on measuring uPA activity, which has been reported to contribute to lung cancer progression." (PMID 26258071, 2015). "In this study, we have extended our findings to show that LMW-HA and HABP2 contribute to lung cancer progression in an uPA-regulated manner." (PMID 26258071, 2015). "Taken as a whole, our data suggest that LMW-HA and HABP2 promote lung cancer progression through uPA-regulated pathways." (PMID 26258071, 2015). "Our results indicate that LMW-HA and HABP2 promote lung cancer oncogenic properties." (PMID 26258071, 2015). "Our data suggest a possible direct effect of HABP2 on uPA activation and lung cancer progression." (PMID 26258071, 2015). "This study examined the functional role of HABP2 on HA-mediated human lung cancer dynamics." (PMID 26258071, 2015). "We provide evidence that HABP2 is an important regulator of lung cancer progression." (PMID 26258071, 2015). "Many lung cancers have changes in their microenvironment including upregulation of the extracellular matrix glycosaminoglycan, hyaluronan (HA), which we have previously demonstrated can regulate the activity of the extracellular serine protease, hyaluronan binding protein 2 (HABP2)." (PMID 26258071, 2015).
nephrotic syndrome (2 papers, 2022). A collection of symptoms that include severe edema, proteinuria, and hypoalbuminemia; it is indicative of renal dysfunction. "Studies of sodium balance revealed that Habp2+/+ and Habp2−/− mice developed renal sodium retention after induction of nephrotic syndrome." (PMID 34870751, 2022). "After induction of nephrotic syndrome, this ratio increased significantly in both genotypes to 53 ± 13 and 46 ± 21 in nephrotic Habp2+/+ and Habp2−/− mice, respectively, without a significant difference between the genotypes (p = 0.49)." (PMID 34870751, 2022). "In a mouse model for nephrotic syndrome, active FSAP was present in nephrotic urine of Habp2+/+ but not of Habp2−/− mice." (PMID 34870751, 2022). "To determine whether FSAP participates in ENaC-mediated sodium retention in vivo, we studied the course of experimental nephrotic syndrome in mice lacking FSAP (Habp2−/−) and their wildtype littermates (Habp2+/+)." (PMID 34870751, 2022).
non-small cell lung carcinoma (2 papers, 2015 to 2024). A group of at least three distinct histological types of lung cancer, including non-small cell squamous cell carcinoma, adenocarcinoma, and large cell carcinoma. "Our observations suggest that exploration of HABP2 in non-small cell lung carcinoma merits further study both as a diagnostic and therapeutic option." (PMID 26258071, 2015). "HABP2 expression was increased in several subtypes of patient non-small cell lung cancer samples." (PMID 26258071, 2015).
Obesity (2 papers, 2007 to 2016). Accumulation of substantial excess body fat. "The upstream region of the HABP2 gene is associated with migraines without aura, and the intergenic region between the PLEKHS1 and MIR4483 genes is associated with obesity − related traits." (PMID 27230431, 2016).
ovarian carcinoma (2 papers, 2019 to 2022). A malignant neoplasm originating from the surface ovarian epithelium. "HABP2, detected in ovarian cancer, was associated with familial nonmedullary thyroid cancer." (PMID 30813883, 2019).
thrombophilia (2 papers, 2011 to 2016). A condition characterized by an abnormally high level of thrombi. "The daughter has a third variant inherited from her mother, the Marburg I polymorphism, in the hyaluronan binding protein 2 (HABP2, Entrez Gene ID 3026) gene known to be associated with inherited thrombophilia, thus contributing to multigenic risk for this trait." (PMID 21935354, 2011).
bacterial pneumonia (1 paper, 2022). Acute infection of the lung parenchyma caused by bacteria (e.g., Streptococcus pneumoniae, Haemophilus influenzae, Chlamydia pneumoniae, Mycoplasma pneumoniae, and Legionella pneumophila). "These alterations were attenuated by PAR2 activation, indicating a possible role for HABP2 in bacterial pneumonia clearance." (PMID 35634317, 2022). "In vivo HABP2 silencing by small interfering RNA attenuated LPS-mediated lung injury and hyperpermeability, indicating a possible therapeutic strategy for bacterial pneumonia in those with AUD-induced barrier dysfunction." (PMID 35634317, 2022).
diabetes (1 paper, 2013). "Up till now, no direct evidence has linked HABP2 with diabetes; however, its ligand, hyaluronan, has been suggested to interact with CD44 and PKC and reduce inflammation in diabetic nephropathy mice." (PMID 23671866, 2013). "Our data showed a decreased HABP2 level in CC carriers, which might give us some hints to find the crosstalk between this protein and diabetes." (PMID 23671866, 2013).
endometritis (1 paper, 2025). An acute or chronic, usually bacterial infectious process affecting the endometrium. "In conclusion, our data demonstrate that PGD2 modulates the release of HMGB-1 and HABP-2 in E. coli-infected endometritis in dairy cows, exhibiting distinct roles at different times." (PMID 40874199, 2025).
Infertility (1 paper, 2018). "Transcriptome studies have shown a significant differential expression of HABP2 transcript in the receptive phase endometrium, with a significant down-regulation observed in women with unexplained infertility compared to fertile women." (PMID 30143058, 2018). "In fact, among infertile women with unexplained infertility, we detected aberrant endometrial HABP2 expression and this group of women presented less frequently the same minor A allele of rs1157916." (PMID 30143058, 2018).
injury (1 paper, 2015). Damage inflicted on the body as the direct or indirect result of an external force, with or without disruption of structural continuity. "The barrier disruptive role of HABP2 were further confirmed by vascular silencing of HABP2 expression, which attenuated the vascular leakiness observed in LPS- and ventilator-induced lung injury." (PMID 26258071, 2015).
melanoma (1 paper, 2020). A malignant, usually aggressive tumor composed of atypical, neoplastic melanocytes. "HABP2 is the extracellular serine protease which play a role in non-small lung cancer progression but its role in melanoma is unknown." (PMID 32195252, 2020). "Interestingly, we have observed the increased abundance of HABP2 in another melanoma cell line RPMI-7951 cell model upon transient knockdown of integrin αV (data not shown, manuscript in preparation)." (PMID 32195252, 2020).
Miscarriage (1 paper, 2018). A pregnancy that ends at a stage in which the fetus is incapable of surviving on its own, defined as the spontaneous loss of a fetus before the 22th week of pregnancy. "The objective of the present study was to investigate the effect of genetic variations of HABP2 in women with idiopathic recurrent miscarriage compared to fertile women." (PMID 30143058, 2018). "A significant decrease in the expression level of HABP2 at the time of implantation has been observed in patients having miscarriage." (PMID 30143058, 2018). "Having this important role in endometrial functions, HABP2 clearly is a potential candidate for studies of recurrent miscarriage." (PMID 30143058, 2018). "Nevertheless, the studied HABP2 gene variants do not seem to be an important contributing factor in recurrent miscarriage." (PMID 30143058, 2018). "Also a significant decrease in the expression level of HABP2 at the time of implantation has been observed in patients having miscarriage." (PMID 30143058, 2018). "Variations in the HABP2 gene did not seem to be involved in the etiology of recurrent miscarriage, while, the number of previous miscarriages had an impact on the live birth rate." (PMID 30143058, 2018).
pancreatitis (1 paper, 2025). Inflammation of the pancreas. "There were no changes in HABP2 levels in patients with pancreatitis compared to controls." (PMID 40885913, 2025).
schizophrenia (1 paper, 2012). A major psychotic disorder characterized by abnormalities in the perception or expression of reality. "Due to the current knowledge of biological role of this gene, HABP2 seems to us as less attractive potential schizophrenia susceptibility gene, compared to TCF7L2, although this may not necessarily be true." (PMID 22247771, 2012).
Thromboembolism (1 paper, 2015). The formation of a blood clot inside a blood vessel that subsequently travels through the blood stream from the site where it formed to another location in the body, generally leading to vascular occlusion at the distant site. "In addition, the G534E mutation of HABP2 is associated with cardiovascular disease and thromboembolism." (PMID 26258071, 2015).
tumor (31 papers, 2006 to 2025). "Functional studies showed that HABP2 had a tumor-suppressive effect, whereas the G534E variant results in loss of function." (PMID 33025555, 2021). "Functional studies have shown that HABP2 has a tumor suppressive effect, whereas the G534E variant results in loss of function." (PMID 33495912, 2021). "Still, for the HABP2 gene recently indicated as tumor suppressor, and for the MAP2K5 gene, encoding a protein kinase that belongs to the MAP kinase family, a possible pathogenic role has been suggested." (PMID 33488516, 2020). "The HABP2 gene encodes for an extracellular serine protease that, upon binding to its ligand hyaluronic acid (HA), activates degradation of the extracellular matrix, including disruption of the endothelium, promoting tumor angiogenesis and cancer metastasis." (PMID 29665850, 2018). "HABP2, on the other hand, is a serine protease that promotes migration, extravasation, tumor growth, and metastasis in lung cancer." (PMID 38724670, 2024). "Using expression studies and cell transformation assays, the study provided evidence that HABP2 is a tumor-suppressor gene." (PMID 27530615, 2016). "RNA expression of HABP2 was tested by qPCR in RNA extracted from tumor and normal thyroid tissue from individuals that are homozygous wild-type or heterozygous for the variant." (PMID 26745718, 2016). "Further, through the use of tumor xenograft models, our results suggest a possible therapeutic role for HABP2 antagonism on cancer growth and metastasis, which merits further research." (PMID 26258071, 2015). "For example, HABP2 expression in certain immune cells may be related to immune evasion or anti-tumor immune responses." (PMID 40092689, 2025). "The HAPB2 G534E variant makes HABP2 lose its tumour inhibition function in familial nonmedullary thyroid cancer." (PMID 38791985, 2024). "The HABP2 gene codes an extracellular protease, which plays a role primarily in coagulation and fibrinolysis but has also been mentioned in adenocarcinoma as an enhancer of tumor progression." (PMID 34503158, 2021). "In addition, LMW-HA enhances these in vitro activities and increases control and HABP2 overexpressing primary tumor volumes in nude mice." (PMID 26258071, 2015). "Importantly, the uPA inhibitor UK122 attenuated LMW-HA- and HABP2-dependent tumor cell motion, migration, and transendothelial extravasation." (PMID 26258071, 2015). "In this study, we investigated the effects of stable silencing or overexpression of HABP2 on HMW-HA and LMW-HA-regulated human NSCLC cell migration, extravasation, tumor growth, and metastasis." (PMID 26258071, 2015). "We observed that HABP2 overexpression in SK-LU-1 human NSCLC cells increased cell motion, migration, transendothelial extravasation, tumor growth and metastasis, and activation of the extracellular serine protease, uPA, implicated in cancer progression." (PMID 26258071, 2015). "HABP2 is a serine protease that binds to hyaluronic acid and modulates the ECM by accelerating the matrix degradation that eventually affects migration, extravasation, tumor growth, and metastasis." (PMID 39058055, 2024). "HABP2 is involved in coagulation and fibrinolysis systems by activating coagulation factor VII and may function as a tumor suppressor, negatively regulating cell proliferation and cell migration." (PMID 38892353, 2024). "On the gel the HABP2 amplicon can be seen in liver but not in thyroid (tumor or adjacent normal tissue) that either carry or don’t carry the variant." (PMID 26745718, 2016). "Based on the results of our qPCR assays and gene expression data published in different databases, we conclude that the HABP2 gene is not expressed in healthy thyroid or tumor thyroid tissue from sporadic PTC cases." (PMID 26745718, 2016). "In addition, increased HABP2 protein expression in tumor samples from affected family members when compared with normal adjacent thyroid tissue and samples from sporadic cancers has been confirmed." (PMID 33495912, 2021).
cancer (13 papers, 2015 to 2024). A tumor composed of atypical neoplastic, often pleomorphic cells that invade other tissues. "It remains possible that the G534E variant in HABP2 is a susceptibility locus for cancer, but further studies are required to determine that." (PMID 27530615, 2016). "While there was considerable variability as indicated by the error bars possibly due to our low sample size (N = 5/condition), we observed a trend toward increased HABP2 expression in several types of NSCLC compared to lung tissue adjacent to cancer." (PMID 26258071, 2015). "The evidence presented was compelling from an in vitro perspective regarding a role for HABP2 rs7080536 in cancer biology, but not as a cancer-predisposing variant." (PMID 28884020, 2017).
cardiovascular disease (4 papers, 2015 to 2024). "The gene symbols like HABP2, PLG, PNPLA3, and TM6SF2 exhibit specific expression in hepatic tissue, and our study also suggests their potential impact on cardiovascular disease." (PMID 38523778, 2024).
infection (2 papers, 2025). The state of being infected such as from the introduction of a foreign agent such as serum, vaccine, antigenic substance or organism. "Immunofluorescence staining of E. coli-infected endometrial explants showed that PGD2 treatment led to an increased expression of HMGB-1 and HABP-2 at 9 h post-infection (P < 0.0001)." (PMID 40874199, 2025). "However, treatment with Grapiprant led to a notable reduction in the mRNA expression levels of HMGB-1 and HABP-2 at 4 and 6 h post-infection (p < 0.0001)." (PMID 40666730, 2025).
HABP2 also shares sentences with these, for which no sentence is quoted: adenocarcinoma (2 papers); blood disorders (2); deep venous thrombosis (2); gastric cancer (2); amyloid diseases (1); Anosmia (1); atrial fibrillation (1); Brain atrophy (1); cannabis dependence (1); colitis (1); colon adenoma (1); coronary artery disease (1); diabetic nephropathy (1); Erythema (1); familial cardiomyopathies (1); glioma (1); glomerular diseases (1); head and neck squamous cell carcinoma (1); Hypertension (1); hypertrophic cardiomyopathy (1); liver cirrhosis (1); lung small cell cancer (1); malaria (1); medullary thyroid cancer (1); migraines (1); nonmedullary thyroid cancer (1); osteosarcoma (1); Pregnancy Loss (1); Sepsis (1); stomach cancer (1).
A further 4 diseases each share a sentence with HABP2 in 1 paper.